IL6 (interleukin 6)
Diseases named in the same sentence as IL6 in open-access papers (continued):
Sharing a sentence is not in itself a finding about the gene and the disease.
Stroke (continued). "Persistently elevated IL-6 levels beyond the acute phase may also predict stroke recurrence and long-term disability." (PMID 40869247, 2025). "The threshold of 2.0 pg/mL may help identify individuals who would benefit from anti-IL-6 drugs to prevent stroke." (PMID 40305179, 2025). "Although IL-6 and CRP are functionally linked, and the release of CRP depends on the IL-6 signaling in the liver, their associations with stroke parameters may differ." (PMID 41221512, 2025). "When combined with neuroimaging findings and clinical scales such as the NIHSS and ASPECTS, certain biomarkers, such as NT-proBNP, troponin, and IL-6 may help predict infarct volume and stroke severity." (PMID 41227149, 2025). "It has been reported that within 1 year after stroke onset, inflammatory markers such as interleukin-6 (IL-6), interleukin-10 (IL-10), and tumor necrosis factor-alpha (TNF-α) are significantly elevated, with notable increases in the IL-6/IL-10 and TNF-α/IL-10 ratios." (PMID 41458124, 2025). "Circulating IL-6 concentrations more than doubled within just 26 min of stroke onset, with a median increase of approximately 28% every two hours, underscoring its potential as a temporal biomarker for estimating stroke onset time." (PMID 41227149, 2025). "After stroke, microglia undergo significant morphological changes, from small branching structures to large amoeba-like structures, that produce pro-inflammatory factors, including IL-1β, IL-6 and TNF-α." (PMID 40004043, 2025). "Elevated interleukin-6 levels were also strongly correlated with stroke occurrence (p = 0.001)." (PMID 41362543, 2025). "However, it is noteworthy that interleukin-6 levels display a notable contrast between stroke and non-stroke groups, which is statistically significant (p = 0.001)." (PMID 41362543, 2025). "Similarly, for stroke the addition of only Eotaxin and IL6 increased the C-statistic from 0.59 to 0.67." (PMID 39695064, 2025). "Studies have indicated the role of SMOX signaling in neuroprotection through various pathways, including antioxidant signaling via Nrf2 in experimental stroke, neuroinflammation in cerebral ischemia via IL6/TNFa, and miR-340-5p/Smurf1 signaling in spinal cord injury." (PMID 40001462, 2025). "A recent systematic review of IL-1, IL-6, and TNF-α levels in aging individuals found only IL-6 levels to be reliably elevated in elderly patients with various disease comorbidities such as sarcopenia, stroke, and liver disease compared to disease-free controls." (PMID 40333142, 2025). "Furthermore, adequate sleep reduces levels of inflammatory cytokines, such as interleukin-6 (IL-6) and tumor necrosis factor-alpha (TNF-α), which have been linked to poor stroke outcomes." (PMID 40004843, 2025). "Our results indicate that the associations between IL-6, MIP-1α, neopterin, QA, and PAr and the cognitive trajectory groups could be at least partly explained by pre-stroke frailty." (PMID 41315409, 2025). "Another indicator of this non-direct pattern of IL-6 in AF is the heterogeneity shown regarding its association with AF-related stroke." (PMID 40980715, 2025). "Understanding the temporal profile and cellular sources of IL-6, as well as its potential transport to the ischemic region in the early phase after a stroke, is crucial for comprehending how this cytokine interacts with potentially salvageable neurons in the ischemic penumbra." (PMID 40305179, 2025). "Another stroke therapy utilizing the potential of IL-6 could be modulation of the trans signaling pathway, enhancing trans signaling at an early stage or suppressing it at a later stage, to avoid a neuroinflammatory response." (PMID 40305179, 2025). "IL-6 is involved in the etiology of atherosclerosis and the stability of atherosclerotic plaques, which may influence the development of a subsequent stroke." (PMID 40305179, 2025).
Stroke (continued). "Five biomarkers, GDF15, IL6, MMP1, MMP7, and TNFR2, were significantly associated with all 6 non-cancer aging-related conditions, mortality, mobility limitation, heart failure, coronary heart disease, stroke, and dementia." (PMID 39695064, 2025). "Following a stroke, immune cells, including dendritic cells and macrophages, detect pathogens and damage signals within the gut, thereby activating local immune responses through the secretion of pro-inflammatory cytokines, such as IL-6, IL-1β, and TNF-α." (PMID 40625834, 2025). "A detailed study of IL-6, focusing on the timing of its administration and the dosing regimen after stroke, may reveal the optimal strategy for achieving therapeutic effects." (PMID 40305179, 2025). "SGLT2 inhibitors demonstrate robust benefits for heart failure and cardiovascular mortality across large CVOTs, with parallel reductions in IL-6, TNF-α, and oxidative stress that may translate to stroke and dementia risk reduction." (PMID 41462689, 2025). "IL-6 has dual effects, exacerbating infarct size and outcomes during the acute phase while promoting tissue repair, neurogenesis, and angiogenesis during the subacute and chronic phases of stroke recovery." (PMID 40095189, 2025). "The level of histamine can also be upregulated by stroke in an age-dependent fashion, which was found to be correlated with the significant increase of plasma pro-inflammatory cytokines such as IL-6, granulocyte colony-stimulating factor (G-CSF), TNF-α and IFN-γ in aged stroke mice." (PMID 39351234, 2024). "Thus, like IL-6, elevated high-sensitivity CRP (hsCRP) has been associated with cognitive decline and recurrent stroke." (PMID 41542283, 2024). "Previous works showed that serum from stroke patients induces endothelial dysfunction likely because of pro-oxidative changes in male Wistar Kyoto rat cerebral and mesenteric arteries or leukocyte-derived IL-6 production in the male Sprague–Dawley rat aorta." (PMID 36536168, 2024). "In PSD, increased IL-6 levels in sera of patients persist up to one year post-stroke diagnosis." (PMID 38421829, 2024). "In addition to Il6, we also observed downregulation of Il1a and Il1b in male stroke brains, and downregulation of Il1r1 in female stroke brains upon genetic ablation of MMP-3." (PMID 39000490, 2024). "In addition, this increase was positively correlated with infarct volume, serum expression of the proinflammatory factor IL-6, and National Institutes of Health Stroke Scale (NIHSS) score." (PMID 37728588, 2024). "Female MMP-3 KO stroke brains showed downregulation of the macrophage classical activation signaling genes Tnf and Tnfsf9, and decreased expression of the acute phage response genes Tnfrsf1a, Jun, Tnfrsf1b, Il6, Tnf, and Fos." (PMID 39000490, 2024). "Interleukins such as IL-1β, TNF-α, and IL-6 can help mitigate the inflammatory response and improve outcomes in stroke patients, which could be another immunomodulation target." (PMID 39633897, 2024). "Female MMP-3 KO stroke brains also had decreased expression of blood cell adhesion genes Pecam1 and Icam2, and decreased expression of inflammatory response genes Ccr1, Cxcl1, Mmp9, Il4ra, Il6, and Il1rn." (PMID 39000490, 2024). "The diverse roles of IL-6 in immunomodulation, tissue repair, neuroprotection, and synaptic plasticity highlight its promising application in neurological conditions ranging from stroke to traumatic brain injury and neurodegenerative diseases." (PMID 39015561, 2024). "Serum concentrations of IL‐6 are significantly elevated after stroke onset." (PMID 39533116, 2024). "Similarly, the pro-inflammatory cytokine interleukin (IL)-6 propels the immune response at early stages of stroke but contributes to neuroprotection and neurogenesis during stroke recovery." (PMID 38279234, 2024).
Stroke (continued). "Our study suggests that somatic mutations in DNMT3A are significantly associated with poor short‐term neurological functional outcomes after stroke, especially in the subgroup of patients with higher hsCRP or IL‐6 levels at baseline and mRS scores at discharge." (PMID 39006763, 2024). "Researchers have proposed an important concept called the “senescence-associated secretory phenotype”, whereby aging brain cells release more proinflammatory signals, such as IL, IL-1α, IL-1β, IL-6, and IL-8, which amplify the inflammatory response after stroke in elderly patients." (PMID 38637850, 2024). "Moreover, serum IL-6 and TNF-α are abnormally elevated among stroke patients (< 24 h), and IL-6 level is positive correlation with stroke severity and poor outcomes." (PMID 38879549, 2024). "After stroke, activated astrocytes not only provide neuroprotection but also adopt toxic functions, such as the release of inflammatory cytokines including interleukins (IL-6, IL-10, and IL-1β), IFN-γ, and TGF-β." (PMID 37728588, 2024). "Inflammatory markers (IL-6 and CRP) are associated with post-stroke cognitive impairment." (PMID 38169754, 2024). "Notably, IL‐6 demonstrates variable roles in different phases of stroke—acute, subacute, and long‐term." (PMID 39533116, 2024). "Furthermore, we observed noteworthy disparities in the plasma levels of IL-2, IL-4, IL-6, IL-10, TNF-α, and INF-γ between patients devoid of risk factors and those presenting with comorbid risk factors associated with stroke." (PMID 38287458, 2024). "EE also inhibited the expression levels of inflammatory cytokines including TNFα, IL-6, and IL-1β, which might facilitate functional recovery after stroke." (PMID 36819784, 2023). "This ratio may approximate functional consequences on individualized stroke therapies, allowing clinicians to determine whether IL‐6 agonists or antagonists should be used at specific time points." (PMID 36478506, 2023). "Interleukin-6 (IL-6) is a key pro-inflammatory molecule and mediates stroke-induced inflammation." (PMID 37805585, 2023). "Interrogating the role of exogenous sgp130 may lead to optimal modulation of the inflammatory signaling pathway, allowing IL‐6 to exert therapeutic effects in stroke." (PMID 36478506, 2023). "Importantly, all these studies measure initial IL‐6 concentrations long after stroke incidence; however, the pro‐inflammatory or anti‐inflammatory impacts of IL‐6 vary significantly depending on the stroke recovery timeline." (PMID 36478506, 2023). "The confirmation of the harmful effect of CCL5 in the acute phase of stroke is supported by the correlation observed between the biomarkers of inflammation, IL-6 and TNF-α, previously determined by our research centre, which is among the first to be released during ischemia in AIS." (PMID 37759440, 2023). "IL-6 stimulates hepatic expression of the downstream marker C-reactive protein (CRP), and elevated circulating levels of both proteins have been associated with increased stroke severity and unfavorable functional outcome." (PMID 37794467, 2023). "However, given these distinctive IL‐6 signaling consequences, IL‐6 is a difficult cytokine to target for stroke therapies." (PMID 36478506, 2023). "Interestingly, human blood plasma samples obtained from stroke patients also showed upregulation of IL-6 levels confirmed at 12 h after stroke, which was also seen in the blood plasma obtained from patients at 24 and 72 h post-stroke." (PMID 37805585, 2023). "Blocking IL‐6 signaling affords beneficial effects in many stroke studies." (PMID 36478506, 2023). "Although IL-6 is a proinflammatory cytokine, it plays a crucial role in cerebral ischemia by acting as a carrier of the inflammatory process during the early phase of stroke and as a neurotrophic factor during the late development of cerebral ischemia." (PMID 36793730, 2023).
Stroke (continued). "The authors of this work hypothesized that the 2.0 pg/mL cut-off of IL-6 could facilitate the selection of individuals that would benefit from anti-IL-6 drugs for stroke prevention." (PMID 37627316, 2023). "While these studies suggest IL‐6 is a detrimental cytokine for stroke prognosis, it rather strengthens the need to better understand the temporality in signaling mechanisms of IL‐6 following stroke." (PMID 36478506, 2023). "Our findings show that IL-6 is one of the strongest inflammation biomarkers for predicting stroke." (PMID 37485268, 2023). "In addition to IL-1β and TNF-α, IL-6 is also a pleiotropic cytokine that is involved in stroke, but its function is still controversial." (PMID 37951917, 2023). "Elevated plasma IL-6 is reported as a feature of post-stroke delirium." (PMID 36769472, 2023). "Higher levels of IL-6 and CRP have been associated with skeletal muscle loss, whereas changes in molecular biomarkers, such as CRP in the blood, urine, and other body fluids, have been associated with post-stroke cognitive decline." (PMID 37373767, 2023). "Indeed IL-6 has been one of the most studied biomarkers of inflammation in stroke patients, especially as a prognostic marker, and as a predictor of stroke risk." (PMID 37485268, 2023). "Due to IL‐6's dominant role in stroke pathology, however, it is vital to understand and specifically target the dynamic IL‐6 signaling pathways that may confer deleterious or beneficial stroke outcomes." (PMID 36478506, 2023). "The present study confirmed the positive associations between stroke severity and IL6 and CKAP4, but also elucidated novel associations, namely between CLEC4G, LY75 and ITGA11, which enrich the present knowledge of blood biomarkers associated with stroke." (PMID 37468969, 2023). "Regarding attempts to resolve functional deficits following stroke, some report measures of IL‐6." (PMID 36478506, 2023). "After stroke, the levels of inflammatory cytokines in patients with cognitive abnormalities are higher than those in patients with normal cognition, such as IL-1β, IL-6, IL-8, IL-10, and IL-12, leading to nerve damage and decreased cognitive function." (PMID 37397457, 2023). "The B/T ratio may be a novel option to optimize IL‐6 targeted therapies for stroke, and further investigation should be conducted to better understand its clinical relevance in stroke." (PMID 36478506, 2023). "Other inhibitions, specific inhibition of the trans‐signaling pathway of IL‐6 using, for example, soluble glycoprotein 130 could be promising therapeutic tools in future stroke research." (PMID 37287421, 2023). "IL-6 is a crucial biomarker for evaluating the stroke severity." (PMID 35838888, 2023). "The level of IL-6 is correlated to stroke intensity and treatment outcome." (PMID 35838888, 2023). "Blocking IL‐6 to exert therapeutic effects may be highly time‐dependent (i.e., acute phase of stroke), complicating the treatment regimen." (PMID 36478506, 2023). "Our analysis corroborates the evidence for its role in the natural history of stroke-related health deterioration, given that many members of the senescence-associated secretory phenotype (SASP; here: SERPINE1, IL6, CRP, TNF and TGFB1) are placed center stage in the interaction network." (PMID 35953740, 2023). "Similarly, nested within the SPS3 trial, the LIMITS study found that among 1,244 patients with lacunar stroke, hsCRP, TNFαR-1 and IL-6 predicted recurrent stroke and vascular events." (PMID 41541100, 2023). "Since the transcript levels of IL-6 in the PBMCs of obese patients were low, leukopenia after stroke might induce lower serum IL-6 levels in obese patients than in lean patients." (PMID 37587512, 2023). "The authors suggested that IL6 may be a potential biomarker for stroke severity and may serve as a therapeutic target for reducing inflammation and tissue damage following stroke." (PMID 37468969, 2023).
Stroke (continued). "Similarly, population-based studies describe a relationship between high levels of IL-6 and the long-term incidence of coronary artery disease, stroke, and peripheral artery disease." (PMID 37175639, 2023). "Using data from the CNSR‐III study, we investigated to what extent, if any, stroke recurrence mediated the relationships between IL‐6 and functional disability at 90 days among patients with acute ischemic stroke and assessed the mediation effect in a series of sensitivity analyses." (PMID 37287421, 2023). "Such a correlation between decreased IFNγ, IL6 levels and spleen atrophy has previously been reported in an experimental stroke model, where increased mortality caused by pneumonia was noted." (PMID 37259163, 2023). "It has been reported that activation of the JAK2/STAT3 pathway could induce the production of IL‐6 and exacerbate stroke‐induced brain injury." (PMID 37143406, 2023). "Therefore, cytokines—particularly TNF, IL-1, and IL-6—have attracted considerable interest as potential markers for stroke severity and neurological outcome." (PMID 38102677, 2023). "However, only the elevation of IL-6 correlated with the severity and prognosis of stroke, and that of other cytokines in plasma proteins after IS appeared secondary to IL-6." (PMID 36547090, 2022). "As evident from our data, RIC therapy alone in diabetic stroke unexpectedly augmented the inflammatory gene expressions significantly as compared to the stroke control group when analyzed for IL-6 (p = 0.0001), IL-1β (p = 0.0002), iCAM-1 (p = 0.030), and iNOS (p = 0.021) at 6 h post-stroke." (PMID 36290774, 2022). "Furthermore, treatment with isorhamnetin in stroke mice improved the integrity of the blood-brain barrier and reduced the levels of IL-1β, IL-6, and TNF-α in the ischemic cortex." (PMID 36160711, 2022). "Still, our present study suggests significant benefits of STVNA treatment, specifically in reducing IL-6 and GM-CSF expression at the cellular level, using our in vitro model of stroke, which signals the need for further investigation, by including, for instance, permeability assays." (PMID 36145501, 2022). "In addition to the link with IL-6, GCs have been involved in the regulation of leukocyte counts in stroke animal models and patients." (PMID 35784349, 2022). "Moreover, IL‐6, a gene promoter, is the main predictor for stroke recurrence in young adults with moderate internal carotid artery stenosis." (PMID 34792838, 2022). "Similarly, other researchers have shown that high plasma levels of IL-6 in post-stroke patients have been correlated with poor prognosis and expansive ischemic lesions." (PMID 36142524, 2022). "Additionally, relating to peripheral inflammatory contributions, adipose-derived MSCs on stroke alter IL-6 signaling to restore BBB integrity and reduce peripheral inflammatory cell infiltration into ischemic brain regions." (PMID 36555094, 2022). "Moreover, COVID-19 severity was shown to be associated with the risk of acute stroke, suggesting that studies on the relationship between the level of IL-6 and breathing in patients with stroke are warranted." (PMID 35629013, 2022). "IL-6 is an early inflammatory signal in the ischemic brain and correlates to the stroke severity." (PMID 35784349, 2022). "Finally, we confirmed that post-stroke treatment of metyrapone (an inhibitor of glucocorticoid synthesis) reduced IL-6 expression and the infarct size in the ischemic brain of diabetic mice." (PMID 35784349, 2022). "IL-1β/IL-6 increased but IL-12p40 decreased in IRF4 CKO vs. flox mice after stroke." (PMID 35963621, 2022). "Elevated plasma IL-6 has been reported to be a signatures of post-stroke delirium." (PMID 35173738, 2022). "In addition, function recovery of stroke by wasp venom treatment was associated with a decrease in TNF-α, IL-1β, IL-6 and inhibition activated microglia as well as apoptosis." (PMID 35171059, 2022).